XRCC3 (X-ray repair cross complementing 3)
Diseases named in the same sentence as XRCC3 in open-access papers (continued):
Sharing a sentence is not in itself a finding about the gene and the disease.
ovarian carcinoma (continued). "This study identified the first RAD51B mutation in a breast and ovarian cancer family and is the first report of XRCC3 mutation analysis in breast and ovarian cancer." (PMID 24139550, 2013). "This study is the first report of XRCC3 mutation screening in breast and ovarian cancer predisposition." (PMID 24139550, 2013). "The present study analysed the five RAD51 paralogs (RAD51B, RAD51C, RAD51D, XRCC2, XRCC3) to estimate their contribution to breast and ovarian cancer predisposition." (PMID 24139550, 2013). "After Bonferroni correction, the meta-analysis showed an association between XRCC3 rs861539 polymorphism and ovarian cancer risk in the heterozygote model and the dominant model (GA vs. GG: OR = 0.88, 95%CI = 0.81-0.96, P = 0.003; GG vs. GA+AA: OR = 0.89, 95%CI = 0.82-0.96, P = 0.004)." (PMID 35978646, 2022). "In an ethnically stratified subgroup analysis, XRCC3 rs861539 was shown to reduce the risk of ovarian cancer in Caucasian in the heterozygote model and the dominant model (GA vs. GG: OR = 0.88, 95%CI = 0.81-0.96, P = 0.004; GG vs. GA+AA: OR = 0.88, 95%CI = 0.81-0.96, P = 0.004)." (PMID 35978646, 2022). "In conclusion, the present meta-analysis suggests that the XRCC3 rs861539 polymorphism may be associated with ovarian cancer risk, especially in Caucasians." (PMID 35978646, 2022). "In the ethnicity-based subgroup analysis, XRCC3 rs861539 was associated with a reduced risk of ovarian cancer in Caucasian populations based on the heterozygote model (GA vs. GG: OR = 0.88, 95%CI = 0.81-0.96, P = 0.004) and dominant model (GG vs. GA+AA: OR = 0.88, 95%CI = 0.81-0.96, P = 0.004)." (PMID 35978646, 2022). "This meta-analysis aims to examine whether the XRCC3 polymorphisms are associated with ovarian cancer risk." (PMID 25006581, 2014). "However, For XRCC3 rs1799794 and rs1799796 polymorphisms, we observed a statistically significant correlation with ovarian cancer risk." (PMID 25006581, 2014). "Identification of families with mutations in the RAD51B, RAD51C or XRCC3 genes and genetic testing of family members could be used to estimate the associated breast and ovarian cancer risks." (PMID 24139550, 2013). "However, a meta-analysis of 5302 cases of ovarian cancer compared to 8075 control cases revealed statistically significant correlation of rs1799794 and rs1799796 polymorphism in XRCC3 and an increased risk of developing ovarian cancer in Caucasians, Asian, and African population." (PMID 31186630, 2019). "Previous studies suggested that XRCC3 rs861539, XRCC2 rs718282, XRCC2 rs3218536, BRCA1 rs1799950, RAD51 rs1801320 and LIG4 rs10131 were associated with the risk of ovarian cancer." (PMID 38890669, 2024). "We preformed the meta-analysis including 5,302 ovarian cancer cases and 8,075 controls for 3 SNPs of XRCC3." (PMID 25006581, 2014). "In this study, we analysed the five RAD51 paralogs (RAD51B, RAD51C, RAD51D, XRCC2, XRCC3) in 142 unrelated patients with breast and/or ovarian cancer to estimate their contribution to breast and ovarian cancer predisposition." (PMID 24139550, 2013). "In view of this, based on the principles and methods of evidence-based medicine, this study objectively evaluated and clarified the impact of XRCC3 rs861539 G>A on the incidence of ovarian cancer, identified the potential mechanism, and provided scientific basis for the prevention of OC." (PMID 37212185, 2023). "No meta-analysis evaluating on the association between the XRCC3 Thr241Met polymorphisms and ovarian cancer risk has been performed." (PMID 24254304, 2014). "However, the two meta-analyses did not include all studies related to XRCC3 rs861539 polymorphism and ovarian cancer risk." (PMID 35978646, 2022). "Nevertheless, the mRNA levels of XRCC3 and XRCC5 were uncorrelated to PFS and OS in ovarian carcinoma patients." (PMID 34539898, 2021). "Mutations in the human RAD51 paralogs (RAD51B, RAD51C, RAD51D, XRCC2, XRCC3, and SWSAP1) are found in a subset of breast and ovarian cancers." (PMID 30551670, 2018).
ovarian carcinoma (continued). "Additionally, we identified some candidate genes linked to reproductive diseases, such as NRG3 and XRCC3 for ovarian cancer, and BAG5, CKB and XRCC3 for endometriosis." (PMID 33477586, 2021). "A significant correlation was revealed between single nucleotide polymorphisms of DNA double-strand break repair genes via homologous recombination (HR) XRCC3-Thr241Met (rs861539), XRCC2--41657C/T (rs718282), BRCA1-Q356R (rs1799950) and RAD51–135 G/C (rs1801320) and ovarian cancer development." (PMID 30712190, 2019).
bladder cancer (15 papers, 2003 to 2022). "Based on the function of XRCC3, mutations in this gene are related to the development of various neoplastic types, such as osteosarcoma, bladder cancer, and thyroid cancer, among others." (PMID 36292754, 2022). "In this study, we found individuals with XRCC3 gene rs1799794 CT, rs861531 AC and rs861530 CT genotypes had a decreased risk of bladder cancer, indicating that the heterozygotes of XRCC3 gene rs1799794, rs861531 and rs861530 are protective genotypes." (PMID 27153553, 2016). "APEX1 rs3136817, MUTYH rs3219493, three SNPs (rs3213356, rs25487 and rs1799782) in XRCC1, and three SNPs (rs1799794, rs861531 and rs861530) in XRCC3 showed significant associations with the risk of bladder cancer." (PMID 27153553, 2016). "In XRCC3 rs861531, compared to the CC genotype, AC genotype showed an association with a decreased risk of bladder cancer (P = 0.008, adjusted OR = 0.47, 95% CI: 0.27-0.82)." (PMID 27153553, 2016). "This XRCC3 exon 7 polymorphism has previously shown a significant association with melanoma, bladder cancer and SCCHN." (PMID 12865926, 2003). "XRCC3 polymorphisms have been associated with melanoma, bladder cancer and SCCHN." (PMID 12865926, 2003). "XRCC3 rs861530 CT genotype showed a decreased risk compared to TT genotype (P = 0.002, adjusted OR = 0.48, 95% CI: 0.30–0.78), and this SNP was associated with an increased risk under recessive model (CC vs. TT + CT, P = 0.001, adjusted OR = 2.19, 95% CI: 1.35–3.55) of bladder cancer." (PMID 27153553, 2016). "Polymorphisms and haplotypes of DNA repair genes are associated with the risk of bladder cancer, and of which the SNPs (rs1799794 and rs861530) in XRCC3 gene might be two major loci in relation to the susceptibility to bladder cancer in a northwest Chinese population." (PMID 27153553, 2016). "The subset of bladder cancer dataset contained 7 SNPs, XRCC3 (rs861539), APE1 (rs3136820), XPD_751 (rs13181), XRCC1_399 (rs25487), XPD_312 (rs1799793), XRCC1_194 (rs1799782), XPC_PAT (rs2228001)." (PMID 27053949, 2016). "Here we aimed to assess the associations of nineteen polymorphisms from seven DNA repair–associated genes (PRAP1, OGG1, APEX1, MUTYH, XRCC1, XRCC2 and XRCC3) with bladder cancer and their interactions in the disease in a Han Chinese population." (PMID 27153553, 2016). "Mutations in DNA repair genes (XRCC3) and variants in genes coding for xenobiotic-transforming enzymes (NAT2, GSTM1, GSTP1 and NQO1) have been shown to modify the susceptibility to bladder cancer." (PMID 19755987, 2009). "Moreover, our findings provide evidence that XRCC3 gene rs1799794 and rs861530 might exert both independent and interactive effects on the bladder cancer." (PMID 27153553, 2016).
glioma (13 papers, 2013 to 2024). A benign or malignant brain and spinal cord tumor that arises from glial cells (astrocytes, oligodendrocytes, ependymal cells). "Our meta-analysis included 30 articles and thus constituted a wide-ranging evaluation of the relationships of ERCC1 C8092A, ERCC2 Lys751Gln, XRCC1 Arg399Gly, and XRCC3 T241M polymorphisms with the risk of glioma in various populations." (PMID 39834980, 2024). "We conducted a comprehensive meta-analysis with the aim of investigating the ERCC1 (rs3212986), ERCC2 (rs13181), XRCC1 (rs25487), and XRCC3 (rs861539) genes to see if there are any risk factors for glioma susceptibility." (PMID 39834980, 2024). "We conducted a comprehensive meta-analysis to investigate the ERCC1 (rs3212986), ERCC2 (rs13181), XRCC1 (rs25487), and XRCC3 (rs861539) genes to see if they are any risk factors for glioma susceptibility." (PMID 39834980, 2024). "We collected eligible studies together to evaluate the association between ERCC1, ERCC2, XRCC1, and XRCC3 polymorphisms and glioma risk in the present study." (PMID 39834980, 2024). "In conclusion, our results show that there is a significant association between the XRCC3 p.Thr241Met polymorphism and increased glioma risk, but only when the homozygous and recessive models were adopted." (PMID 36264998, 2022). "The XRCC3 p.Thr241Met (rs861539) polymorphism has been extensively studied for its association with glioma risk, but results remain conflicting." (PMID 36264998, 2022). "We demonstrated that the XRCC3 p.Thr241Met polymorphism is associated with an increased risk of glioma only in the homozygous and recessive models." (PMID 36264998, 2022). "To clarify this, we performed a meta-analysis to further investigate the association between the XRCC3 p.Thr241Met polymorphism and glioma risk." (PMID 36264998, 2022). "Of the polymorphisms in XRCC3, only p.Thr241Met (rs861539) has been frequently studied with respect to its association with glioma risk." (PMID 36264998, 2022). "As both protein structure and expression can be affected by genetic polymorphisms, a number of GWAS have investigated the association between XRCC3 polymorphisms and risk for cancers, including gliomas." (PMID 36264998, 2022). "Strong evidence for the association between XRCC3 C18607T polymorphism and glioma risk was found in a meta-analysis." (PMID 26249370, 2015). "The present study aimed to investigate the association between the XRCC3 Thr241Met polymorphism and the susceptibility to glioma." (PMID 25013509, 2014). "The findings of the present study indicate that the XRCC3 Thr241Met polymorphism is associated with a susceptibility to glioma." (PMID 25013509, 2014). "Although the association between the XRCC3 Thr241Met polymorphism and glioma risk have been extensively investigated, the currently available results are inconclusive." (PMID 25013509, 2014). "In conclusion, the present study indicates that the XRCC3 Thr241Met polymorphism is associated with a susceptibility to glioma." (PMID 25013509, 2014). "The present study aimed to investigate the association between the XRCC3 Thr241Met polymorphism and the potential susceptibility to gliomas." (PMID 25013509, 2014). "XRCC1 Arg194Trp, XRCC1 Arg399Gln, and XRCC3 C241T, appear to be associated with susceptibility to glioma in a Chinese population." (PMID 23385236, 2013). "For instance, carriers of both XRCC1 Gln399Gln and XRCC3 Met241Met were associated with a three-fold increased risk of glioma." (PMID 23383237, 2013). "The XRCC3 241T/T genotype was associated with a strong increased glioma risk (OR = 3.78, 95% CI = 1.86–9.06)." (PMID 23385236, 2013). "Therefore, in this work, we meticulously performed a systematic review and meta-analysis to investigate the association between the XRCC3 p.Thr241Met polymorphism and glioma risk." (PMID 36264998, 2022). "Summary of the association between XRCC3 p.Thr241Met polymorphism and glioma risk." (PMID 36264998, 2022).
glioma (continued). "We detected a statistically significant association between the XRCC3 p.Thr241Met polymorphism and increased glioma risk when the homozygous model and the recessive model were applied (homozygous, OR = 1.381, 95% CI = 1.081–1.764, P = 0.010; recessive, OR = 1.305, 95% CI = 1.140–1.493, P<0.001)." (PMID 36264998, 2022). "It is also known that XRCC3 polymorphisms play an important role in the treatment of gliomas." (PMID 36264998, 2022). "In the ethnicity-based subgroup analysis, we again found a statistically significant association between XRCC3 p.Thr241Met and increased glioma risk in the homozygous (OR = 1.704, 95% CI = 1.358–2.317, P<0.001) and recessive models (OR = 1.305, 95% CI = 1.140–1.493, P<0.001) in the Asians." (PMID 36264998, 2022). "The DNA repair gene, X-ray repair cross-complementing group 3 (XRCC3) Thr241Met polymorphism may be associated with a susceptibility to glioma." (PMID 25013509, 2014). "Thus, a screening test that will include the ERCC1 (rs3212986), ERCC2 (rs13181), XRCC1 (rs25487), and XRCC3 (rs861539) genes may well be helpful for the prevention and earliest treatment of patients with glioma susceptibility." (PMID 39834980, 2024). "Furthermore, our meta-analysis examined only one polymorphism, whereas analysis of multiple genetic polymorphisms in the same gene might provide a more complete picture of the role of XRCC3 in mediating glioma risk." (PMID 36264998, 2022). "We identified 30 eligible studies investigating the PubMed records (up to January 2024) via a mishmash of the subsequent terms: brain tumors, glioma, glioblastoma, gene associations, SNPs, XRCC1, XRCC3, ERCC1, and ERCC2." (PMID 39834980, 2024). "Using an isogenic glioma cell line, in which XRCC3 was downregulated by interference RNA, they demonstrated its importance as a possible target for therapeutic intervention." (PMID 37298600, 2023). "Mitochondria are known to enhance temozolomide chemoresistance, suggesting a role for XRCC3 in the treatment of gliomas." (PMID 36264998, 2022). "By downregulating the expression of XRCC3 by interference RNA, it was proved that XRCC3 can protect glioma cells from germ-cell death, apoptosis, and cell cycle inhibition induced by temozolomide." (PMID 35978646, 2022). "When stratified by the grade of the glioma, the patients with stage IV glioma (according to the World Health Organization classification) had a significantly higher frequency of the XRCC3 241 MetMet genotype (OR=1.61; 95% CI: 1.06–2.44; P=0.03)." (PMID 25013509, 2014). "The glioma patients had a significantly higher frequency of the XRCC3 241 MetMet genotype [odds ratio (OR) = 1.62; 95% confidence interval (CI): 1.09–2.41; P=0.02] compared with the control subjects." (PMID 25013509, 2014). "Patients with glioma had a significantly higher frequency of the XRCC3 241 MetMet genotype (OR=1.62; 95% CI: 1.09–2.41; P=0.02) compared with the control subjects." (PMID 25013509, 2014). "When stratified by the grade of glioma, patients with stage IV glioma had a significantly higher frequency of the XRCC3 241 MetMet genotype (OR=1.61; 95% CI: 1.06–2.44; P=0.03)." (PMID 25013509, 2014). "Further analysis of the interactions of two susceptibility-associated SNPs, XRCC1 Arg194Trp and XRCC3 Thr241Met, showed that the combination of the XRCC1 194T and XRCC3 241T alleles brought a large increase in glioma risk (OR = 2.75, 95% CI = 1.54–4.04)." (PMID 23385236, 2013). "Here we investigate the role of 10 potential SNPs in XRCC3, BRCA2, RAG1, XRCC5, LIG4, XRCC4 and ATM in the development of gliomas, and further evaluate their gene-gene and gene-environment interactions in the development of glioma." (PMID 23663450, 2013). "We genotyped 10 potentially functional single nucleotide polymorphisms (SNPs) in 7 DNA double-strand break repair pathway genes (XRCC3, BRCA2, RAG1, XRCC5, LIG4, XRCC4 and ATM) in a case–control study including 384 glioma patients and 384 cancer-free controls in a Chinese Han population." (PMID 23663450, 2013).
thyroid cancer (13 papers, 2007 to 2025). "In the Iranian population, the rs861539 polymorphism in XRCC3 showed a significant association with the risk of thyroid cancer." (PMID 38892180, 2024). "Only the combined variants of the RAD52, XRCC2, and XRCC3 genes showed an increased risk of thyroid cancer, as we wrote about in Section 3.2." (PMID 38892180, 2024). "Notable differences in the impact of XRCC3 polymorphisms on thyroid cancer risk between the studied populations suggest that genetic and environmental influences play a key role in this context." (PMID 38892180, 2024). "More studies are needed, taking into account genetic and environmental differences, to better understand the complexity of the association between XRCC3 polymorphisms and thyroid cancer risk in different populations." (PMID 38892180, 2024). "In the various populations, polymorphisms in the XRCC3 gene showed conflicting effects on the risk of thyroid cancer." (PMID 38892180, 2024). "We conducted a comprehensive meta-analysis to explore the association of polymorphisms at XRCC1, XRCC2 and XRCC3 genes with susceptibility to thyroid cancer (TC)." (PMID 34319046, 2021). "As an example, the association of polymorphisms in DNA repair genes XRCC1 (rs25487, rs1799782) and XRCC3 (rs861539) with thyroid cancer risk and progression can be considered." (PMID 29178884, 2017). "Two other studies identified the combinations of RAD52 2259C > T, XRCC2 R188H and XRCC3 T241M polymorphisms and RAD51 Exon1/59G > T, XRCC3 Thr241Met variant alleles to have predictive value for the polygenic risk of thyroid cancer." (PMID 24723911, 2014). "A XRCC3 18067T polymorphic allele was similarly shown to be associated with differentiated thyroid cancer." (PMID 23185308, 2012). "However, the same study found that the combination of the XRCC1 rs25487 and XRCC3 rs861539 genotypes contributed to an increased risk of thyroid cancer." (PMID 38892180, 2024). "The results of meta-analyses regarding polymorphisms of the XRCC3 gene in thyroid cancer are mixed." (PMID 38892180, 2024). "In the particular context of thyroid cancer, interestingly, multiple studies, including a meta-analysis, have suggested the XRCC3 rs861539 variant T allele and/or, in particular, the TT homozygous genotype to be associated with increased risk of TC or, more specifically, PTC." (PMID 31374908, 2019). "This difference could be related to impaired homologous recombination as the 18067T allele variant of XRCC3 was more frequent in 134 thyroid cancer patients than in 166 healthy patients in another study." (PMID 17712314, 2007). "The most frequently associated genes with thyroid cancer found on PubMed were BAX, XRCC1, XRCC3, XPO5, IL-10, BRAF, RET, and K-RAS." (PMID 37211566, 2023). "Moreover, it was discovered that the interaction of allele variants of the XRCC3 rs861539 and RAD51 rs1801321 genes may significantly influence the risk of developing thyroid cancer, depending on the histological subtype of the tumor." (PMID 38892180, 2024).